CXCR3 (C-X-C motif chemokine receptor 3)
Diseases named in the same sentence as CXCR3 in open-access papers (continued):
Sharing a sentence is not in itself a finding about the gene and the disease.
metastasis (1 paper, 2025). The spread or migration of cancer cells from one part of the body (where they first appeared) to another. "CXCR3 is prevalently expressed by CD49a+NK cell subsets in mouse and human liver metastasis." (PMID 40168086, 2025).
metastatic prostate carcinoma (1 paper, 2012). A carcinoma that arises from the prostate gland and has spread to other anatomic sites. "Our studies for the first time demonstrated that both CXCR3 mRNA and protein expression was upregulated in human localized prostate cancer and metastatic prostate cancer." (PMID 22236567, 2012). "In addition, CXCR3B, the dominant CXCR3 splice variant in normal prostate epithelial cells (RWPE-1), was replaced in part by CXCR3A in invasive and metastatic prostate cancer cell lines (DU-145 and PC-3) and promoted cell motility and invasiveness in vitro." (PMID 22236567, 2012).
morbid obesity (1 paper, 2023). An excess of body weight, normally defined as an individual with a body mass index greater than 35 or a body weight greater than one hundred percent of ideal body weight. "Furthermore, we found an increased population of monocytic CD14+, HLA-DR-, CD11b+, CXCR3+ cells in patients with morbid obesity and an overall reduction of the HLA-DR monocytic expression compared to the control population." (PMID 37266430, 2023). "Apart from that, we described highly affected, distinct immune cell subsets, defined as CD127+ memory T cells and monocytic CD14+, HLA-DR, CD11b+, CXCR3+ cells, that might play a significant role in understanding and further decoding the etiopathogenesis of morbid obesity." (PMID 37266430, 2023).
mycobacteriosis (1 paper, 2016). "A recent study underlined that bi-allelic RORC loss-of-function mutations resulted in the absence of IL-17-producing T cells and defective IFNγ production by circulating γδ T cells and CD4+CCR6+CXCR3+ αβ T cells, and was associated with mycobacteriosis." (PMID 27409590, 2016). "Indeed, CD4 T cell responses to Mtb are contained in a CXCR3+CCR6+ Th subset, cells that produce IFNγ, IL-2 and TNFα, and a mutation leading to the loss of the CXCR3+CCR6+ lineage specific transcription factor RORC leads to mycobacteriosis." (PMID 27409590, 2016).
myocardial ischemia (1 paper, 2023). A disorder of cardiac function caused by insufficient blood flow to the muscle tissue of the heart. "Taken together, our data suggest that trafficking of CD4+ TEM cells in response to acute myocardial ischemia may be orchestrated in an IP-10 – CXCR3 dependent manner controlling cardiac repair in AMI." (PMID 37426649, 2023).
nasal polyps (1 paper, 2014). "In contrast, 9 out of 11 samples showed both CCR4 and CXCR3 expression of T cell in non-asthmatic nasal polyps." (PMID 25361058, 2014).
neovascular age-related macular degeneration (1 paper, 2022). "Peripheral T cell CXCR3 expression has been found uniquely lower in patients having neovascular age-related macular degeneration (nAMD) than in healthy individuals." (PMID 35709177, 2022).
neuromyelitis optica (1 paper, 2013). A rare inflammatory disease of the central nervous system characterized mainly by attacks of uni- or bilateral optic neuritis (ON) and acute myelitis. "Notably, these CD138+HLA-DR+ plasmablasts overexpress CXCR3, whose ligands are present in the cerebrospinal fluid during the relapse of neuromyelitis optica." (PMID 24340077, 2013).
non-alcoholic fatty liver (1 paper, 2020). A benign form of fatty non-alcoholic fatty liver disease where the disease has not yet progressed to the inflammation of liver. "The frequencies of peripheral CXCR3+ IFN-γ+ T-bet+ and IL-17A+ iNKT cells were also increased in NASH patients in comparison with those in non-alcoholic fatty liver (NAFL) patients or healthy controls." (PMID 32765518, 2020).
nonalcoholic fatty liver disease (1 paper, 2023). "The application of 2‐DG or the deletion of cell‐specific PKM2 can diminish the presence of specific CXCR3+ Th17 (ihTh17) cells in nonalcoholic fatty liver disease (NAFLD), ultimately mitigating the NAFLD driven by Th17 cells." (PMID 38098611, 2023).
Oral ulcer (1 paper, 2017). Erosion of the mucous mebrane of the mouth with local excavation of the surface, resulting from the sloughing of inflammatory necrotic tissue. "Consistent with our data, CXCR3-expressing T lymphocytes as well as levels of Th1 cytokines including interleukin (IL)−8, IL-12 and interferon γ have been shown to be increased in oral ulcers of BD patients compared to healthy controls." (PMID 29116188, 2017).
oropharynx carcinoma (1 paper, 2023). A primary or metastatic malignant neoplasm that affects the oropharynx. "In this manuscript, we demonstrated a particular chemokine axis (CXCR3/CXCL9,10,11) to be highly expressed in HPV-associated oropharynx carcinoma (HPVOPC)." (PMID 37686653, 2023).
oropharynx squamous cell carcinoma (1 paper, 2023). A squamous cell carcinoma that involves the oropharynx. "Taken together, these results suggest that CXCR3 inhibition in oropharynx squamous cell carcinoma should be used with caution, as these agents may stimulate tumor growth considering the competing effects of this cytokine axis." (PMID 37686653, 2023).
papilloma (1 paper, 2020). A benign epithelial neoplasm that projects above the surrounding epithelial surface and consists of villous or arborescent outgrowths of fibrovascular stroma. "We found a novel regulator, stress keratin 17 (K17), was induced in expression following MmuPV1 infection, and that K17 was critical for preventing T cell infiltration in MmuPV1-induced papillomas by inhibiting the CXCL9/CXCL10/CXCR3 axis." (PMID 31968015, 2020). "In contrast, most papillomas in K17KO mice treated with anti-CXCR3 persisted or grew between week 4 and week 6 (right bar graph and lower middle graph)." (PMID 31968015, 2020). "We blocked CXCR3 in K17KO mice using anti-CXCR3 blocking antibody, starting 4 days before infection and continuing until 6 weeks post-infection, and followed papilloma growth." (PMID 31968015, 2020). "The CXCR3 blocking antibody increased the incidence as well as the size of papillomas in the K17KO mice to levels comparable to that observed in the WT mice." (PMID 31968015, 2020). "When we blocked CXCR3, the papillomas in K17KO mice increased significantly in size, despite a reduction in CXCL11 level." (PMID 31968015, 2020). "Ten out of 14 infected ear sites (71%, red line) developed papilloma at 4 weeks post-infection in K17KO mice treated with isotype control while 12 out of 12 infected ear sites developed papilloma in K17KO treated with anti-CXCR3 antibody at 4 weeks post-infection (100%, dashed black line)." (PMID 31968015, 2020). "At 6 weeks post-infection, we quantified infiltrating CD4+ and CD8+ T cells in the remaining papillomas that did not completely regress in K17KO control mice, papillomas in K17KO mice blocked with anti-CXCR3 and papillomas in untreated WT mice." (PMID 31968015, 2020). "There were decreases in both infiltrating CD4 and CD8 T cells in the papillomas arising in K17KO blocked with anti-CXCR3, suggesting the increased infiltration of CD8+ T cells in K17KO mouse papillomas was mediated by the CXCL9/CXCL10/CXCR3 signaling axis." (PMID 31968015, 2020).
Parkinson disease (1 paper, 2026). A progressive degenerative disorder of the central nervous system characterized by loss of dopamine producing neurons in the substantia nigra and the presence of Lewy bodies in the substantia nigra and locus coeruleus. "Immune dysregulation is involved in Parkinson's disease (PD), but the roles of C-X-C motif chemokine receptor 3 (CXCR3)/chemokine receptor 6 (CXCR6) on T cells and their correlation with peripheral inflammation remain unclear." (PMID 41656499, 2026).
pericarditis (1 paper, 2019). An inflammatory process affecting the pericardium. "CXCR3 and CXCL13 may serve as predictive markers of clinical manifestations, including pericarditis and arthralgia, in patients with AOSD." (PMID 31101882, 2019).
peripheral T-cell lymphoma, not otherwise specified (1 paper, 2024). Aggressive nodal or extranodal mature (peripheral) T-cell lymphomas that do not belong to the better defined entities of the remainder of mature T-cell lymphomas. "Based on gene expression profiling, Amador and colleagues recently assessed Th1 (Tbet and CXCR3) and Th2 (GATA3 and CCR4) protein expression using the IHC algorithm in cases of nodal and extranodal peripheral T-cell lymphoma, not otherwise specified (PTCL, NOS)." (PMID 38474383, 2024).
peritonitis (1 paper, 2019). Inflammation of the peritoneum (tissue that lines the abdominal wall and covers most of the organs in the abdomen). "In murine peritonitis models, blockage of CXCR3 or CXCL10 in conjunction with antibiotic therapy reduced migration of NK cells to the peritoneal cavity and improved survival, even if applied after induction of peritonitis." (PMID 31440239, 2019).
pharyngitis (1 paper, 2022). Inflammation of the throat most often caused by viral and bacterial infections. "Unsupervised UMAP analysis also confirmed the lower CXCR3 expression on γδTCR + Vδ2+ T cells and MAIT cells in participants that developed pharyngitis." (PMID 35140232, 2022). "To further elucidate functional immune responses during acute S. pyogenes pharyngitis, we analysed cells for CD69 expression (a marker of activation), CXCR3 (a marker of migration) and intracellular perforin and granzyme-B expression (cytotoxic proteins involved in cell lysis)." (PMID 35140232, 2022).
pneumococcal infection (1 paper, 2020). Infections with bacteria of the species streptococcus pneumoniae. "Decreases in CXCL9, − 10, and − 11 levels reduced CXCR3 and PI3K/Akt expression in PM2.5 + pneumococcus co-treated macrophages, compared with that for pneumococcal infection alone." (PMID 32753046, 2020).
Pneumocystis pneumonia (1 paper, 2012). "By contrast, in a murine model of Pneumocystis pneumonia, it was shown that overexpression of IP10 in lungs led to increased migration of CXCR3+CD8+ T-cells to the lung followed by accelerated Pneumocystis clearance." (PMID 23056449, 2012).
polyarticular JIA (1 paper, 2021). "Our results are concordant with prior work limited to oligo and the closely related seronegative polyarticular JIA, which also highlighted a predominance of cells expressing either CXCR3 or IFN-γ in JIA SF." (PMID 34403374, 2021).
polymyositis (1 paper, 2014). A rare idiopathic inflammatory myopathy characterized by symmetric proximal muscle weakness and elevated muscle enzymes. "We investigated the role of the CXCL10/CXCR3 axis using a murine model of polymyositis based on a previous study on the chemokine profile of human IIM." (PMID 24939012, 2014).
Q fever (1 paper, 2017). A bacterial infection caused by Coxiella burnetii. "We also focused on the capacity of IFN-γ induced CXCR3-chemokines to monitor disease activity in chronic Q fever." (PMID 28793883, 2017). "Further analysis of the CXCR3-chemokine serum concentrations revealed that samples taken within one month after diagnosis of chronic Q fever (n = 9) were significantly higher for CXCL9 (p < 0.05) and CXCL10 (p < 0.05) than samples taken more than 1 month after diagnosis (n = 41)." (PMID 28793883, 2017).
radiation pneumonitis (1 paper, 2023). Inflammation of the lung due to harmful effects of ionizing or non-ionizing radiation. "Our study revealed that CXCL10/CXCR3 activation in radiation pneumonitis leads to increased NK cell infiltration, while the accumulation of reactive oxygen species (ROS) causes excessive autophagy, thereby inhibiting NK cell function." (PMID 38077388, 2023). "These related studies underscore the evident connection between CXCR3 and ROS, making the investigation of their interplay in radiation pneumonitis a key focus of our ongoing research." (PMID 38077388, 2023). "The activation of the CXCL10/CXCR3 axis exacerbated radiation pneumonitis by inducing excessive autophagy, thereby hindering NK cells from clearing damaged tissue cells and hyper-reactive inflammatory cells." (PMID 38077388, 2023).
retinal disease (1 paper, 2024). "Blocking immune responses generally, or via targeting the chemokine receptor CXCR3, did not exacerbate retinal disease but instead prevented pathology despite retinal MCMV infection." (PMID 39565860, 2024).
retinal ischemia (1 paper, 2015). A ischemic disease that involves the retina. "Given that CXCL10 and its receptor CXCR3 are involved in retinal inflammation and neuronal injury, it would be important to understand the potential mechanisms underlying the upregulation of this pathway after retinal ischemia." (PMID 26448323, 2015). "The expression of CXCL4, which binds with low affinity to CXCR3, was elevated after retinal ischemia though expressed later than CXCL10." (PMID 26448323, 2015). "The mRNA and protein expression levels of CXCL10 and CXCR3 were significantly increased after IOP-induced retinal ischemia." (PMID 26448323, 2015). "To determine whether the activation of CXCR3 is involved in oxidative and nitrosative stress after retinal ischemia, we examined the formation of peroxynitrite in retinal lysates." (PMID 26448323, 2015). "CXCR3 mRNA was also rapidly upregulated after retinal ischemia." (PMID 26448323, 2015). "Together, these data indicate that the activation of CXCR3 pathway mediates microglia/monocyte recruitment and activation and retinal inflammatory reactions after IOP-induced retinal ischemia." (PMID 26448323, 2015).
retinitis (1 paper, 2022). Inflammation of the retina. "To validate whether the CXCR3-CXCL 9, 10, 11 axis is over-expressed similarly in case of retinitis (HR) and gastro-enteric (HG) patients belonging to group 1, we compared the relative mRNA expression of some of the components of the CXCL9, 10, 11-CXCR3 axis along with some downstream effectors." (PMID 35538132, 2022).
rhabdomyosarcoma (1 paper, 2022). A rare aggressive malignant mesenchymal neoplasm arising from skeletal muscle. "The gene expression of IFN-γ, perforin, Gzma, and CXCR3 in CD8+ T cells isolated from both rhabdomyosarcoma-bearing wild-type and APN−/− mice were quantified by RT-PCR." (PMID 35530361, 2022).
salmonellosis (1 paper, 2017). Infections with bacteria of the genus salmonella. "Our data suggests that CXCR3 is a key molecule in host intestinal immunity against Salmonellosis via regulating neutrophils chemotaxis." (PMID 28860493, 2017). "Herein, we explored the role of CXCR3 in the clearance of live S. typhimurium bacteria and in the recruitment of leukocytes during both acute and chronic salmonellosis." (PMID 28860493, 2017). "The protective role of CXCR3 during salmonellosis may be attributed to its neutrophil chemotactic function during infection with gram-negative intracellular bacteria." (PMID 28860493, 2017). "Macrophages, also express CXCR3, play an important role in controlling salmonellosis." (PMID 28860493, 2017). "CXCR3-mediated neutrophil migration to the mucosa seems particularly important during the early stages of infection for localising and preventing S. typhimurium dissemination, however its significance during chronic Salmonellosis remains unclear." (PMID 28860493, 2017).
sarcoma (1 paper, 2013). A usually aggressive malignant neoplasm of the soft tissue or bone. "Accordingly in order to determine whether TDLN/Tumor derived T cells in NLGP-treated animals are expressing more chemotactic components over PBS mice, we assessed CD8+ T cells for their expression of CXCR3 and corresponding ligands on day 21 sarcoma mice." (PMID 23326300, 2013). "Interestingly, CXCR3 and CCR5 expression was unchanged on sarcoma cells upon in vitro NLGP treatment." (PMID 23326300, 2013).
Senile plaques (1 paper, 2014). Senile plaques are extracellular deposits of amyloid in the gray matter of the brain. "Notably, the expression of IP-10 and CXCR3 is up-regulated in the brains of AD, where CXCR3 is expressed constitutively on neurons, while IP-10 expression is enhanced in a subset of reactive astrocytes surrounding senile plaques." (PMID 24691121, 2014).
septic shock (1 paper, 2012). Shock caused by infection; frequently caused by gram negative bacteria, although some cases have been caused by other bacteria, viruses, fungi, and protozoa; characterized by fever, chills, tachycardia, tachypnea, and hypotension. "Likewise, we reported that the numbers of intraperitoneal CXCR3+ NK T cells did not change during the course of CLP-induced septic shock." (PMID 22992408, 2012).
serous ovarian cancers (1 paper, 2017). "Herein, we first screened two independent cohorts of high-grade serous ovarian cancers (HGSCs, discovery set n=60, validation set n=117) and 102 metastatic lesions for CXCR3 expression." (PMID 28504691, 2017).
small cell lung carcinoma (1 paper, 2023). Small cell lung cancer (SCLC) is a highly aggressive malignant neoplasm, accounting for 10-15% of lung cancer cases, characterized byrapid growth, and early metastasis. "CXCL9 derived Th1 responses and limited Th2 infiltration, and it was associated with favorable prognosis in small cell lung cancer, however, other studies have reported that CXCL9 binds to CXCR3 in tumors to promote EMT and cancer cell migration." (PMID 38075694, 2023).
streptococcal pharyngitis (1 paper, 2009). Inflammation of the throat due to Streptococcus pyogenes. "The three CXC chemokines CXCL9, 10, and 11 are closely related, act through the same receptor (CXCR3), are expressed in the context of streptococcal pharyngitis, are antibacterial towards S. pyogenes, and are induced by the cell wall-anchored M protein from S. pyogenes." (PMID 19274094, 2009).
T cell-deficiency (1 paper, 2024). "Thus, in addition to CD4 T cell-deficiency, elevated IFN-γ concentrations also contribute to downregulation of CD127 and CXCR3 on memory P14 T cells in MHCII−/− mice." (PMID 38806459, 2024).
thymoma (1 paper, 2024). A neoplasm arising from the epithelial cells of the thymus. "Before therapy, patients with MG showed a reduction in the frequency of chemokine receptor 3 (CXCR3)+ CD4+ T cells, especially in the thymoma group; however, CXCR3+ CD8+ T cells remained normal." (PMID 38378668, 2024).
thyroid nodule (1 paper, 2016). A small circumscribed mass in the THYROID GLAND that can be of neoplastic growth or non-neoplastic abnormality. "In addition, the expression of CXCR3 and CCR5 was upregulated in neoplastic thyroid nodules as compared to the hyperplastic ones." (PMID 27872865, 2016).
toxoplasmosis (1 paper, 2024). A parasitic disease contracted by the ingestion or fetal transmission of toxoplasma gondii. "So, it is likely that the upregulated inflammatory genes, such as Ccl5, Ccl3, Ccl7, Ccr5, and Cxcr3, could be the key factors that cause mouse reproductive organ damage, and then contribute to the tragic pregnancy outcomes of toxoplasmosis." (PMID 39006750, 2024).
trigeminal neuralgia (1 paper, 2025). Trigeminal neuralgia is a nerve disorder that causes a stabbing or electric-shock-like pain in parts of the face. "In a mouse model of trigeminal neuralgia, CXCL10 binds explicitly to CXCR3, inducing activation of the PI3K/AKT signaling pathway." (PMID 41249857, 2025).
urinary tract tumors (1 paper, 2025). "In addition to PD-1/PD-L1 inhibitors, recent studies have also highlighted the importance of other immune checkpoints, such as CXCR3 and IL-15, in regulating the immune response to urinary tract tumors." (PMID 40066439, 2025).